ENSG00000288640 (novel protein)
Gene: Protein-coding gene on chromosome 7 (112,450,460 to 112,490,941, forward strand). Ensembl gene ENSG00000288640.
Genetic constraint (gnomAD): Missense variants: 431 observed, 469.79 expected, observed/expected ratio (o/e) 0.92, 90% interval 0.85 to 0.99. Synonymous variants: 152 observed, 164.83 expected, observed/expected ratio (o/e) 0.92, 90% interval 0.81 to 1.05.